GALNT2 (polypeptide N-acetylgalactosaminyltransferase 2)
Diseases named in the same sentence as GALNT2 in open-access papers (continued):
Sharing a sentence is not in itself a finding about the gene and the disease.
otitis media (2 papers, 2022 to 2023). Inflammation of the anatomical structures of the middle ear, which is most often caused by an infectious process. "Mutant Galnt2 homozygote (Galnt2tm1Lat/tm1Lat) mimics human otitis media in comparable pathology and causes hearing loss." (PMID 36874359, 2022). "The mouse model with a mutation in the Galnt2 (Galnt2tm1Lat/tm1Lat) was explored in this study as a novel model of human otitis media." (PMID 36874359, 2022). "Exon 7 deletion in Galnt2 mouse was originally intended to be elaborated in a study on the lungs, but it was unexpectedly discovered that mice have otitis media." (PMID 36874359, 2022). "Moreover, upregulation of Muc5ac and Muc5b in Galnt2 mutant mice resulted in increased middle ear effusion and decreased mucociliary clearance, thereby preventing otitis media." (PMID 36874359, 2022).
acute monocytic leukemia (1 paper, 2016). Acute monoblastic leukemia (AML-M5), is one of the most common subtypes of acute myeloid leukemia (AML) that is either comprised of more than 80% of monoblasts (AML-M5a) or 30-80% monoblasts with (pro)monocytic differentiation (AML-M5b). "In myeloid cells, the expression of GALNT2, GALNT4, GALNT5 and GALNT7 was observed in K562 cells (chronic myeloid leukemia line), and of GALNT1, GALNT2, GALNT3 and GALNT4 in SHI-1 (acute monocytic leukemia line)." (PMID 27322213, 2016).
asthma (1 paper, 2013). "GALNT2 rs2144300, previously associated with HDL-C in European Americans and African Americans, has not previously been associated with lung function or asthma quantitative traits." (PMID 23382687, 2013).
atopic dermatitis (1 paper, 2024). "In the combined dataset, the expression of galactose-deficient IgA1-associated genes (including GALNT2, GALNT12, C1GALT1, C1GALT1C1 and ST6GALNAC2) were compared between atopic dermatitis patients and healthy controls." (PMID 39119579, 2024).
chronic pancreatitis (1 paper, 2025). A chronic inflammatory process causing damage and fibrosis of the pancreatic parenchyma. "Overexpression of the Tn antigen, generated by combining Cosmc-knockout with GalNT2 overexpression, resulted in chronic pancreatitis with acinar cell loss, fibrosis, immune cell infiltration and consecutive progressive pancreatic atrophy in the later stages." (PMID 40175689, 2025).
clear cell renal cell carcinoma (1 paper, 2024). "However, the significance of GALNT2 in clear cell renal cell carcinoma (ccRCC) progression remains largely undetermined." (PMID 38478152, 2024).
cognitive decline (1 paper, 2025). "Unlike GALNT2 and TRMT2A, whose evidence of involvement in AD are limited, MFGE8 (a.k.a. medin) is strongly linked to AD, as it interacts directly with amyloid-β to promote its aggregation and it is associated with cognitive decline." (PMID 40602528, 2025).
colon cancer (1 paper, 2023). "Taken together, these results suggest that AXL is involved in GALNT2‐promoted invasiveness in colon cancer cells." (PMID 36409270, 2023). "We demonstrated that TAM receptors are O‐glycosylated and GALNT2 promotes invasive behaviors of colon cancer cells partly through modification of O‐glycosylation and protein stability of AXL." (PMID 36409270, 2023). "We showed that GALNT2 promoted colon cancer cell migration and invasion in vitro and peritoneal metastasis in vivo." (PMID 36409270, 2023). "Because metastasis is a critical determinant of cancer deaths, we therefore focused on the effect of GALNT2 on colon cancer cell migration and invasion, which are important in vitro phenotypes of metastasis." (PMID 36409270, 2023). "Collectively, our data demonstrated that GALNT2 can generate O‐glycans on AXL and regulate AXL protein levels in colon cancer cells." (PMID 36409270, 2023). "We have also found that GALNT2 was able to mildly regulate the phosphorylation of EGFR and MET in colon cancer cells." (PMID 36409270, 2023). "GALNT2 can modify O‐glycans on AXL to increase AXL protein levels and in turn promote colon cancer cell invasiveness." (PMID 36409270, 2023). "Moreover, the GALNT2‐mediated invasion of colon cancer cells was almost blocked by AXL inhibitors or siRNAs, suggesting that AXL is a crucial determinant in the GALNT2‐mediated invasiveness." (PMID 36409270, 2023). "Here, we found that GALNT2 knockdown suppressed the activity of EGFR and MET in colon cancer cells." (PMID 36409270, 2023). "With respect to whether GALNT2 can regulate ligand‐dependent activation of AXL, unfortunately, we could not detect sufficient amount of phospho‐AXL in colon cancer cells to draw a conclusion." (PMID 36409270, 2023).
colorectal tumors (1 paper, 2023). "In this study, GALNT2 is overexpressed in colorectal tumors and correlates with poor prognosis." (PMID 36409270, 2023). "In this study, immunohistochemistry showed that GALNT2 was overexpressed in colorectal tumors compared with the adjacent nontumor tissues." (PMID 36409270, 2023). "Data from the Hong and TCGA Colorectal Statistics indicated that GALNT2 is overexpressed in colorectal tumors compared with the normal colorectal tissues." (PMID 36409270, 2023). "We found that GALNT2 protein was overexpressed in colorectal tumors compared with their adjacent nontumor tissues." (PMID 36409270, 2023).
congenital muscular dystrophy (1 paper, 2014). A muscular dystrophy that is characterized by diminished muscle tone (hypotonia), progressive muscle weakness and degeneration (atrophy), abnormally fixed joints, spinal rigidity, and delays in reaching motor milestones such as sitting or standing unassisted. "An additional candidate gene mapped in the linked region is GALNT2, a glycosylating enzyme similar to B3GALNT2 recently found mutated in another form of congenital muscular dystrophy, and also involved in the O-glycosylation of peptides in the Golgi apparatus." (PMID 25353622, 2014).
diabetic retinopathy (1 paper, 2024). "In the present study, we found that apo-CIII glycosylation (specifically, sialylation) and the linked GALNT2-gene variant were associated with the prevalence and incidence of diabetic retinopathy." (PMID 38791405, 2024). "The most pronounced finding of this study was the connection between GALNT2, apo-CIII glycosylation, and diabetic retinopathy." (PMID 38791405, 2024).
hearing loss (1 paper, 2022). "This study suggests the reason that OM in Galnt2 mutant mice is highly associated with hearing loss, which is mainly presented as a dysfunction of the Eustachian tube, mucosa proliferation, and capillary expansion." (PMID 36874359, 2022).
hyperalphalipoproteinemia (1 paper, 2012). An autosomal dominant genetic condition caused by mutation(s) in the CETP gene, encoding cholesteryl ester transfer protein. "Taken together, we show that rare coding and splicing mutations in LIPG, CETP, and GALNT2 are enriched in persons with hyperalphalipoproteinemia and segregate with elevated HDLc in families." (PMID 22952570, 2012).
hyperlipidaemia (1 paper, 2016). "Assessment of the association between the DOCK7, PCSK9 and GALNT2 loci identified through GWAS 28, 29, 30 with the risk of hyperlipidaemia has become fundamental in the validation of these signals." (PMID 26493351, 2016). "Third, although we have detected the interactions of the DOCK7, PCSK9 and GALNT2 SNPs on hyperlipidaemia in this study, many unmeasured environmental and genetic factors still need to be considered." (PMID 26493351, 2016). "Although the association of some DOCK7, PCSK9 and GALNT2 SNPs and serum lipid levels has been reported in several previous studies, the association of the novel variants and their haplotypes and possible gene–gene interaction with the risk of hyperlipidaemia has never been detected previously." (PMID 26493351, 2016).
IgA nephropathy (1 paper, 2022). "It was found that GALNT2 expression was negatively modulated by let-7b in IgA nephropathy." (PMID 36058918, 2022).
inflammatory bowel disease (1 paper, 2022). A spectrum of small and large bowel inflammatory diseases of unknown etiology. "GALNT2 can catalyze the O-glycosylation of a variety of proteins, including the hinge region of immunoglobulin A1 and mucin, participating in the occurrence and development of inflammatory bowel diseases." (PMID 35370688, 2022).
intellectual impairments (1 paper, 2025). "However, our recent study of a novel CDG caused by deficiency in GALNT2 is showing more severe and multisystemic phenotypes with neurodevelopmental and intellectual impairments." (PMID 40449597, 2025).
leukemia (1 paper, 2016). A malignant (clonal) hematologic disorder, involving hematopoietic stem cells and characterized by the presence of primitive or atypical myeloid or lymphoid cells in the bone marrow and the blood. "Through a CGH array analysis, we next extracted five candidate genes (GALNT2, DCHS2, ENTPD8, PNPLA7, FBXW7) involved in drug resistance in leukemia cells." (PMID 28025493, 2016).
lymph node metastasis (1 paper, 2016). "Low GALNT2 expression correlated with increased tumor depth, lymph node metastasis, and TNM stage." (PMID 26848976, 2016).
ovarian carcinoma (1 paper, 2022). A malignant neoplasm originating from the surface ovarian epithelium. "Upregulation of GALNT2 and GALNT6 resulted in enhanced migration and invasion of oral and ovarian cancer cells, in part by increasing O-glycosylation and activation of the EGFR." (PMID 35028012, 2022).
pancreatic ductal adenocarcinoma (1 paper, 2024). An infiltrating adenocarcinoma that arises from the epithelial cells of the pancreas. "Future studies should investigate whether GalNT2 overexpression or alterations in O-glycosylation play a central role in the development of pancreatic ductal adenocarcinoma (PDAC)." (PMID 39613794, 2024).
rectum adenocarcinoma (1 paper, 2022). An adenocarcinoma arising from the rectum. "In addition, pan-cancer analysis showed that the increased expression of GALNT2 also predicted unfavorable prognosis in several other cancers, including HNSC, KIRC, LUAD, LUSC, STAD, rectum adenocarcinoma (READ) and uterine corpus endometrial carcinoma (UCEC)." (PMID 36110252, 2022).
renal carcinoma (1 paper, 2024). A carcinoma arising from the epithelium of the renal parenchyma or the renal pelvis. "In addition, GALNT2 over-expression accelerated proliferation of renal cancer cell (RCC) lines." (PMID 38478152, 2024).
T-cell leukemia (1 paper, 2016). A malignant disease of the T-lymphocytes in the bone marrow, thymus, and/or blood. "In contrast, GALNT2 has also been associated with deterioration due to human T cell leukemia." (PMID 28025493, 2016).
ulcerative colitis (1 paper, 2022). An inflammatory bowel disease involving the mucosal surface of the large intestine and rectum. "Studies have shown that GALNT2 is upregulated in ulcerative colitis patients in the active stage compared with patients in the remission period." (PMID 35370688, 2022).
vascular occlusion (1 paper, 2022). "This is the first study showing that the low expression of genes associated with epigenetic regulation, such as SOX6 and RBM33, may be related to vascular occlusion in MMD, whereas the overexpression of KCNMA1 and GALNT2 may be related to the vascular hyperplasia." (PMID 35368875, 2022).
tumor (20 papers, 2012 to 2025). "GALNT2 has been demonstrated to suppress malignancy in several cancers, and its dysregulation has been implicated in tumor progression." (PMID 30557297, 2018). "In summary, our experimental validation reinforces the bioinformatics predictions by confirming the overexpression of several risk genes, including GALNT2, in LUAD tissues compared to adjacent non-tumor tissues." (PMID 38596689, 2024). "In the mouse model, GALNT2 knockdown significantly decreased the number of peritoneal tumor nodules." (PMID 36409270, 2023). "In line with previous observations, tumor oncosphere formation ability of GSCs was significantly restrained following GALNT2 depletion." (PMID 37000153, 2023). "As one member of GALNT family, GALNT2 is dysregulated in many types of cancers, and plays tumor suppressive or promoting roles via regulating protein O-glycosylation, such as epidermal growth factor receptor and AXL receptor tyrosine kinase." (PMID 37993881, 2023). "As expected, silencing GALNT2 dramatically restricts tumor growth and augments the survival of mice." (PMID 37000153, 2023). "Next, tumor oncosphere formation assay, a standard golden technique for detecting cancer stem cell self-renewal, was used to evaluate the potential effect of GALNT2 expression on sustaining GSCs self-renewal." (PMID 37000153, 2023). "We discovered that the sizes and weights of tumors in the GALNT2 knockdown group were smaller than those in the control group; thus, knockdown of GALNT2 suppressed tumor formation in vivo." (PMID 36058918, 2022). "Together, these functional studies illustrated that GALNT2 exerted a tumor-promoting property in NSCLC." (PMID 36058918, 2022). "Polypeptide N-acetylgalactosaminyltransferase 2(ppGalNAc-T2), which catalyzes initiation of mucin-type O-glycosylation, is also involvedin tumor migration and invasion." (PMID 22992780, 2012). "Importantly, it is also O-glycosylated by a polypeptide GalNAc-transferases (GALNT2 and GALNT6) that add the first GalNAc to serine or threonine amino acids giving rise to tumor-associated Tn-antigen." (PMID 35028012, 2022). "In vivo experiments demonstrated that knockdown of GALNT2 restrained tumor formation in nude mice." (PMID 36058918, 2022). "However, additional functional experiments are needed to reveal more detailed information about the role of GALNT2 in anti-tumor immune response." (PMID 36110252, 2022). "High expression of GALNT2 exhibited a tumor-promoting function in NSCLC." (PMID 36058918, 2022). "In gastric adenocarcinoma, downregulation of GALNT2 increased the cell proliferation, migration, invasion and tumor metastasis by increasing the phosphorylation of hepatocyte growth factor receptor (MET: a receptor tyrosine kinase like IGF-l) and decreasing the expression of the Tn antigen on MET." (PMID 27322213, 2016). "In addition, positive GALNT2 expression significantly correlated with younger age at diagnosis, early clinical stage, primary tumor originated from the extra-adrenal site, favorable INPC histology and MYCN non-amplification." (PMID 25362349, 2014). "GALNT2 knockdown repressed NSCLC cell proliferation, migration, and invasion and restrained tumor formation in nude mice." (PMID 41174058, 2025). "Our results indicated significant overexpression of GALNT2, MTHFD1, FAM207A, KRT81, and IKZF3 in tumor tissues, consistent with our bioinformatics analysis." (PMID 38596689, 2024). "KIF20A and GALNT2 were elevated, whereas GRIA1 expressions were suppressed in tumor tissues, compared with adjacent normal tissues." (PMID 36524130, 2022). "In the TCGA dataset, mRNA levels of four genes (CNIH1, KIF20A, GALNT2, and AP3S1) were highly expressed in tumor tissues, while GRIA1 levels were downregulated in tumor tissues." (PMID 36524130, 2022). "GALNT2 functions as an oncogenic driver in NSCLC proliferation, migration, and invasion in vitro, and its knockdown restrained tumor formation in vivo." (PMID 36551208, 2022).
tumor (continued). "Apart from GRIA1, upregulated mRNA levels of CNIH1, KIF20A, GALNT2, and AP3S1 were observed in tumor tissues in these datasets." (PMID 36524130, 2022). "Suppressing GALNT2 expression in GCA cells increased cell growth, migration, and invasion in vitro, and tumor metastasis in vivo." (PMID 26848976, 2016). "GALNT2 can modify IGF-1R O-glycosylation and interfere with IGF-1-triggered dimerization and activity of IGF-1R, thereby regulating downstream signaling events related to malignant properties of NB cells in vitro and tumor growth in vivo." (PMID 25362349, 2014). "Among the GTs highlighted in this process GALNT1, GALNT2 and GALNT3, members of the UDP-N-α-D galactosamine:polypeptide N-acetylgalactosaminyltransferases (GALNT) family, were described to be involved in different biological processes, including tumor progression, proliferation, and migration." (PMID 40096084, 2025).
cancer (14 papers, 2016 to 2025). A tumor composed of atypical neoplastic, often pleomorphic cells that invade other tissues. "Alterations in GALNT2 activity have been implicated in various diseases, such as cancer, metabolic disorders, and cardiovascular diseases, highlighting its importance in maintaining normal physiological functions." (PMID 39613794, 2024). "Additional reports have discussed mutations of GALNT2 in cancers." (PMID 28025493, 2016). "Copy number variations (CNVs) affecting GALNT2 are commonly found in various cancers, whereas gene amplifications are more common than deletions." (PMID 39613794, 2024). "Our findings support that GALNT2 modulates cancer cell behaviors by activating multiple RTKs with varying degrees." (PMID 36409270, 2023). "Mechanistically, we demonstrated that AXL, an emerging target for cancer therapy, was a novel protein substrate of GALNT2 and GALNT2 regulated AXL degradation primarily through the proteasome‐dependent pathway." (PMID 36409270, 2023). "To characterize GALNT2 abundance in human cancers, we examined GALNT2 expression using the TCGA pan-cancer data." (PMID 36058918, 2022). "Mucin glycosylating enzyme GALNT2 modulates mucin O-glycosylation, and has been revealed as a regulator of tumorigenesis in various cancers." (PMID 36110252, 2022). "GALNT2 is involved in several types of metabolic diseases and cancer pathology." (PMID 39020437, 2024). "Consistent with previous reports suggesting a crucial role of AXL in cancer cell migration, invasion, and metastasis, our results showed that GALNT2‐mediated invasion was significantly reversed by inhibiting AXL expression with pharmacologic or genetic approach." (PMID 36409270, 2023). "GALNT2 gene is a Mucin O-glycosylase which is disputed for its effect in cancers." (PMID 36060650, 2022). "A study thought that GALNT2 may promote cancer progression via activating EGFR/PI3K/Akt/mTOR pathway." (PMID 36060650, 2022). "Furthermore, it was also considered that GALNT2 can inhibit cancer development by reducing MET phosphorylation in some conditions, and it was found that cg17737409 site methylation in GLANT2 was helpful for patient's prognosis in this study." (PMID 36060650, 2022). "We discovered that the expression of GALNT2 was widely elevated across numerous cancers." (PMID 36058918, 2022). "In contrast, GALNT2 is related to malignant phenotypes in a number of other cancer types." (PMID 34069424, 2021). "GALNT2 can also modify the activity of EGFR or the IGF-1 receptor in cancer." (PMID 26848976, 2016). "Thus, the O‐glycosylation sites on EGFR and MET initiated by GALNT2 could vary in different cancer types, which leads to differential effects of GALNT2 on the activities of EGFR and MET." (PMID 36409270, 2023). "Thus, GALNT2 may suppress the malignant phenotype of cancer cells by preventing the activation of EGFR and its downstream signaling pathway." (PMID 34069424, 2021). "Regarding initiation of GalNAc-type O-glycosylation, GALNT2, GALNT3, GALNT6, GALNT7, and GALNT14 were highly expressed in both cancer types, LUAD and LUSC." (PMID 40718829, 2025). "Among the 5 cancer cell lines, AGS and MKN28 cells expressed higher levels of GALNT2, whereas MKN45 cells expressed lower levels of GALNT2." (PMID 26848976, 2016). "The second explanation could be that GALNT2 initiates O‐glycosylation at the same sites on EGFR and MET, but the glycosyltransferases for further modification of the O‐glycans are differentially expressed in different cancer types." (PMID 36409270, 2023).